CCND1 (cyclin D1)
Diseases named in the same sentence as CCND1 in open-access papers (continued):
Sharing a sentence is not in itself a finding about the gene and the disease.
breast cancer (continued). "Since breast cancer is notable for the high incidence of cyclin D1 aberrations with up to 50% of tumors expressing elevated levels of the protein, we can expect to find p16 defects among the remaining tumors." (PMID 20174572, 2010). "Amplification of the gene has been detected in about 15% of breast cancers, while overexpression of cyclin D1 at mRNA and protein levels is seen in up to 50% of primary tumors, mostly ER-positive and well-differentiated tumors." (PMID 20174572, 2010). "Transactivations of ER-α machinery, as well as the enhancement in nuclear accumulation of β-Catenin also support the observed upregulation of cyclin D1 in Wnt1/ILK double-transgenic mammary tumors." (PMID 20565980, 2010). "Cyclin D1 is solidly established as an oncogene with a pivotal role in pathogenesis of breast cancer." (PMID 21176227, 2010). "This suggests a reduction of glycolysis in tumor cells and, therefore, such as in mammary tumor cells, a paradoxical role of cyclin D1." (PMID 20459741, 2010). "Cyclin D1 is one of the most commonly overexpressed genes in human breast cancer whose transcription is activated by FOXA-1-mediated ER-α gene regulation, as well as by β-catenin-mediated transcriptional machinery." (PMID 20565980, 2010). "CCND1 is one of the most commonly overexpressed genes in breast cancer (up to 50% of breast cancers)." (PMID 20543978, 2010). "Activated GSK-3β has been shown to inhibit cyclin D1 expression in tumor cells including breast cancer cells and squamous cancer cells of the tongue." (PMID 20704706, 2010). "A positive correlation between nuclear EGFR and cyclin D1 expression was observed both in mammary gland samples and breast cancer samples of cancer-bearing TA2 mice." (PMID 20092659, 2010). "Cyclin D1 is overexpressed in >50% and amplified in 15% of breast cancer cases and acts as a mitogenic sensor by responding to oncogenes and various growth factors, including E2." (PMID 20525379, 2010). "AGR2 affects key breast cancer drivers, including cyclin D1, c-Myc, and ER, as well as more general oncogenic signaling nodes such as p-Src and survivin." (PMID 20525379, 2010). "Breast cancer cells over-expressing cyclin D1 are resistant to 4OH-Tam and the level of cyclin D1 is negatively correlated to responsiveness to 4OH-Tam." (PMID 21092078, 2010). "All together, these findings suggest that BEX2 expression is required for c-Jun-mediated induction of cyclin D1 and cell proliferation in breast cancer cells." (PMID 20482821, 2010). "Breast cancer drivers (ER and cyclin D1) as well as cancer-signaling nodes (pSrc, c-Myc, and survivin) were demonstrated to be downstream of AGR2." (PMID 20525379, 2010). "Nonetheless, ERK signaling can activate AP-1 which can play an important role in cell proliferation, apoptosis, differentiation, cancer cell invasion and has been shown to regulate cyclin D1 and E2F in breast cancer cells." (PMID 20858281, 2010). "Directly overexpressing Cyclin D1 in mammary tissue in transgenic mice using the mouse mammary tumor virus (MMTV) promoter leads to breast cancer, demonstrating that Cyclin D1 is sufficient for tumorigenesis." (PMID 20548776, 2010). "Real-time PCR analysis determined that the downstream targets of FOXO3a, including cell-cycle inhibitors p21Cip1 and p27Kip1 were significantly downregulated, while the regulator cyclin D1 was upregulated in miR-96 transfected breast cancer cells." (PMID 21203424, 2010). "We recently reported that dietary administration of AUR delayed onset of N-methylnitrosourea-induced mammary carcinomas in rats, which corresponded to a decrease in cyclin D1 protein expression." (PMID 20932318, 2010).
breast cancer (continued). "Culture of MCF-7 breast cancer cells with 10 μM CGK733 induced a detectable decline of cyclin D1 levels within 2 h of exposure, and this effect was maximal between 4 and 6 h after exposure." (PMID 19903334, 2009). "In comparison, western blot analysis of rat mammary tumors (n = 10 per group) confirmed that auraptene (500 ppm) significantly reduced (p < 0.05) cyclin D1 expression by 49% compared to the MNU only group." (PMID 19640308, 2009). "Overexpression of cyclin D1, which is found to be overexpressed in 60–80% of breast cancer tumors, inhibits the transcriptional activity of DMP1 and antagonizes its function." (PMID 19671193, 2009). "In a recent study in a Tissue Micro Array (TMA) format, we have shown that cyclin D1 protein is over expressed in the local breast cancer patients." (PMID 19640308, 2009). "Following the in vitro studies, the chemopreventive effects of auraptene were assessed in the MNU-induced rat mammary carcinogenesis model and the expression of cyclin D1 in mammary tumors was analyzed by western blot." (PMID 19640308, 2009). "STA-21 treatment of cells disrupted Stat3/DNA complexes, abrogated Stat3 translocation into the nucleus, inhibited expression of proteins such as Bcl-XL and Cyclin D1 and induced the apoptosis of breast cancer cell lines." (PMID 19274102, 2009). "In breast cancer cells, Sox2 interacts with β-catenin to cooperatively regulate the cyclin D1 promoter through the −74 bp binding site as well." (PMID 19479035, 2009). "It is presumed that estrogen and insulin/IGF-1 regulate c-Myc and cyclin D1 during breast cancer cell proliferation." (PMID 19865540, 2009). "Western blot analysis of rat mammary tumors (n = 10 per group) confirmed that auraptene (500 ppm) significantly reduced (p < 0.05) cyclin D1 expression by 49% compared to the MNU only group." (PMID 19640308, 2009). "Consistent with the cell culture results, auraptene also significantly decreased cyclin D1 in the rat mammary tumors." (PMID 19640308, 2009). "A HLA-A0201 positive human breast cancer cell line MDA-MB-231 was chosen because of its high expression of cyclin D1." (PMID 19707583, 2009). "In summary, dietary auraptene delayed MNU-induced median time to tumor and significantly suppressed cyclin D1 expression in the rat mammary tumors." (PMID 19640308, 2009). "We are further studying the mechanism of regulation of cyclin D1 by auraptene and its downstream effects in human breast cancer cell lines." (PMID 19640308, 2009). "Overall, this study shows that auraptene significantly delayed the time to tumor and suppressed cyclin D1 which is a cell cycle protein that has been shown to play a major role in breast cancer." (PMID 19640308, 2009). "Amplification of the cyclin D1 gene has been identified in approximately 15 to 20% of human breast cancers while overexpression of the protein has been demonstrated in a higher percentage." (PMID 19874578, 2009). "In this work, we observe that CGK733 induces the loss of cyclin D1 via the ubiquitin- dependent proteasomal degradation pathway in MCF-7 and T47D breast cancer cell lines." (PMID 19903334, 2009). "In Ontario, the heterozygote (medium activity) [OR: 1.66, 95%CI (1.18–2.33)] and high activity [OR: 2.22, 95%CI (1.49–3.28)] combinations of CCND1 and COMT genotypes showed statistically significant association with increased breast cancer risk." (PMID 18194538, 2008). "We have previously reported amplification of one such oncogene, namely CCND1, to be correlated with an adverse effect of tamoxifen in premenopausal breast cancer patients." (PMID 18823530, 2008). "In this study, we have investigated the contribution of independent and the combined effects of CCND1 Pro241Pro and COMT Met108/158Val polymorphisms to breast cancer risk in two independent Caucasian populations from Ontario and Finland." (PMID 18194538, 2008).
breast cancer (continued). "To verify these findings, we first examined the expression of Cyclin D1 which has previously been shown to be repressed by ectopic expression of Ebp1 in human breast cancer cell lines." (PMID 19094237, 2008). "In sensitive breast cancer lines, the reduction in cyclin D1 led to release of sequestered CDK inhibitors, p27Kip1 and p21Cip1, and association of these inhibitors with cyclin E/CDK2 complexes." (PMID 19046439, 2008). "In this study, we have shown a combined effect between the two commonly occurring polymorphisms associated with higher enzymatic activity of CCND1 and COMT in the context of breast cancer predisposition." (PMID 18194538, 2008). "Our results suggest a genetic cross-talk between the medium and higher enzymatic activity allele combinations of CCND1 and COMT in breast cancer development." (PMID 18194538, 2008). "Using two independent Caucasian populations, we have shown a stronger combined effect of the two commonly occurring CCND1 and COMT genotypes in the context of breast cancer predisposition." (PMID 18194538, 2008). "Cyclin D1 is a key cell cycle regulatory protein, known to be up-regulated by estrogen, an established breast cancer mitogen." (PMID 18334030, 2008). "This leads to the activation of MAPK and to subsequent up-regulation of cyclin D1 in breast cancer cells." (PMID 18665217, 2008). "Rapamycin and its analogs, which are currently in late-stage clinical trials in breast cancer, inhibit mTOR kinase, a key regulator of cyclin D1." (PMID 19077306, 2008). "Mammary tumors from the control group had a significantly higher (about 5.6-fold) expression of cyclin D1 in comparison with animals treated with estradiol alone or estradiol plus progesterone." (PMID 17257424, 2007). "This was further correlated to the expression of Cyclin D1 that was increased in high-grade breast cancer." (PMID 17668048, 2007). "In MDA-MB-468 breast cancer cells which express lower levels of cyclin D1, treatment with this concentration of rapamycin reduced the level of cyclin D1 to near undetectable levels within 6 h." (PMID 17407548, 2007). "Trichostatin A (TSA) is a prototype HDACI that has been shown to induce cyclin D1 degradation in human breast cancer and transformed rat kidney fibroblast cell lines." (PMID 17407548, 2007). "Exogenously expressed αB crystallin was able to restore the rapid degradation of cyclin D1 in the MCF-7 breast cancer cell line." (PMID 17407548, 2007). "The expression of SMAR1 is drastically downregulated during breast cancer progression and is inversely correlated with Cyclin D1 expression." (PMID 17668048, 2007). "Taken together, these findings demonstrate that rapamycin activates GSK3β and induces the phosphorylation dependent degradation of cyclin D1 via the ubiquitin pathway in breast cancer cell lines." (PMID 17407548, 2007). "Here we show that downmodulation of SMAR1 in high grade breast carcinoma is correlated with upregulated Cyclin D1 expression." (PMID 17668048, 2007). "Determination of coamplification rates of major oncogenes such as MYC and CCND1 in breast carcinomas should provide important information regarding prognosis." (PMID 17262082, 2007). "Recent studies in our laboratory have demonstrated that TSA induces the rapid degradation of cyclin D1 in MCF-7 breast cancer cells and to a lesser extent in several other cell lines." (PMID 16503970, 2006). "While the CCND1 gene is amplified in up to 20% of human breast cancers, cyclin D1 protein is overexpressed in over 50% of human mammary carcinomas." (PMID 16536875, 2006).
breast cancer (continued). "For example, in mammary epithelial or breast cancer cells, cyclin D1 mRNA expression can be regulated by estrogen receptor alpha (ER) binding to regulatory regions within the cyclin D1 locus." (PMID 16863592, 2006). "Several lines of evidence point to an important role for both cyclin D1 as well as EMS1/cortactin in breast cancer formation." (PMID 16536875, 2006). "While cyclin D1 is frequently amplified and/or overexpressed in breast cancer, cyclin D1 overexpression is rarely observed in prostatic tumors." (PMID 16863592, 2006). "Cyclin D1 is an important regulator of G1-S phase cell cycle transition and has been shown to be important for breast cancer development." (PMID 16504004, 2006). "Drug-induced cyclin D1 ablation protects against breast cancer development, inhibits cancer cell proliferation and thus presents an important therapeutic strategy for treating and/ or preventing breast cancer." (PMID 16504004, 2006). "We have previously shown that TSA induces cyclin D1 degradation and the apparent nuclear exclusion of ectopically expressed GFP-cyclin D1 in human breast cancer cell lines." (PMID 16503970, 2006). "Cyclin D1 ablation has been shown to provide specific protection against breast cancer and can overcome drug resistance by sensitizing these cells to apoptotic signals." (PMID 16504004, 2006). "Drug-induced cyclin D1 repression not only inhibits breast cancer cell proliferation but also sensitizes these cells to other agents such as CDK and Akt inhibitors." (PMID 16504004, 2006). "Drug induced cyclin D1 repression contributes to the inhibition of breast cancer cell proliferation and can sensitize cells to CDK and Akt inhibitors." (PMID 16504004, 2006). "We have demonstrated previously, that TSA induces the ubiquitin-dependent degradation of cyclin D1 in MCF-7 breast cancer cells." (PMID 16503970, 2006). "We have previously shown that the histone deacetylase inhibitor trichostatin A (TSA) induces the rapid ubiquitin-dependent degradation of cyclin D1 in MCF-7 breast cancer cells prior to repression of cyclin D1 gene (CCND1) transcription." (PMID 16504004, 2006). "Cyclin D1 ablation thus presents an important therapeutic strategy for the treatment of human breast cancer." (PMID 16504004, 2006). "For this purpose, we treated MCF-7 breast cancer cells with sub-apoptotic doses of sanguinarine and studied cyclin D1 and topoisomerase II behavior by immunocytochemical methods." (PMID 16512916, 2006). "We have demonstrated previously, that TSA specifically induces the rapid ubiquitin-dependent degradation of cyclin D1 in MCF-7 breast cancer cells." (PMID 16503970, 2006). "In the original study, 5 out of 9 MMTV-cyclin D1 (MP1) mice developed mammary tumors with a mean age of 76 weeks." (PMID 16536875, 2006). "In order to better clarify the role of cyclin D1 in breast cancer we analysed a material of randomised postmenopausal breast cancer patients with long follow-up." (PMID 15138475, 2004). "It has further been shown that cyclin D1 overexpression can affect tamoxifen response in breast cancer cell lines, but contradictory results have nevertheless been published regarding this potentially important feature for cyclin D1." (PMID 15138475, 2004). "Cyclin D1 gene amplification in sporadic tumours as well as cyclin D1 RNA expression in ERα positive breast cancer has been correlated to poor prognosis." (PMID 15138475, 2004). "Our results suggest that cyclin D1 overexpression predicts for tamoxifen treatment resistance in breast cancer, which is line with recent experimental data using breast cancer cell lines and overexpression systems." (PMID 15138475, 2004).
breast cancer (continued). "Overexpression of cyclin D1 is observed in a fraction of cases with DCIS and invasive breast cancer, and when studying precancerous forms of breast cancer the breakpoint for increased cyclin D1 expression has been observed between ADH and DCIS." (PMID 14612904, 2003). "These promising clinical perspectives call for a sensitive, accurate and rapid method to screen breast cancer patients for CCND1 amplification/overexpression." (PMID 11870541, 2002). "This study confirms that CCND1 is an ER-responsive or ER-coactivator gene in breast cancer, and points to the CCND1 gene as a putative molecular marker predictive of hormone responsiveness in breast cancer." (PMID 11870541, 2002). "A recent study showed that antiestrogen-induced p21 and p27 via ER blocked entry of G1 phase cells into the S phase by inhibiting cyclin D1 expression and cdk2 kinase activity in breast cancer cell lines." (PMID 12085261, 2002). "In conclusion, we observed a major link between CCND1 mRNA status and ER status, confirming a role for the CCND1 gene as an ER-responsive gene or ER-coactivator gene in breast cancer." (PMID 11870541, 2002). "Overexpression of G1-S regulators cyclin D1 or cyclin A is frequently observed in breast cancer and is also to result in ligand-independent activation of oestrogen receptor in vitro." (PMID 11875707, 2002). "Clinical studies have found amplification of 11q13 chromosomal region (which contains CCND1) in 10–15% of human primary breast cancers." (PMID 11870541, 2002). "Previously reported in vitro data suggest that CCND1 overexpression is dependent on the presence of oestrogen and oestrogen receptors, and that anti-oestrogens inhibit cyclin D1 expression in breast cancer cells." (PMID 11870541, 2002). "Overexpression of cyclin D1 is generally found in OR-α-positive, more differentiated breast cancer, whereas overexpression of cyclin A is associated with OR-α-negative, undifferentiated breast cancer (this study)." (PMID 11875707, 2002). "For example, over-expression of Cyclin D1 has been shown to distinguish breast carcinomas and in situ breast lesions from benign lesions." (PMID 12177779, 2002). "In order to evaluate the pathological relevance of cyclin D1 overexpression in human breast cancer, we generated a polyclonal antiserum against the carboxy-terminal part of the cyclin D1 protein." (PMID 8611372, 1996). "Due to the intrinsic regulation between circFOXK2 and CCND1, we demonstrated that circFOXK2 plays a pivotal role in breast cancer progression and endocrine therapy resistance by stabilizing CCND1 mRNA, thereby promoting CCND1 expression and facilitating tumor growth." (PMID 40233410, 2025). "The Cyclin D1 gene plays a crucial role in cell cycle regulation by G1-S transition induction through Cdk4 and Cdk6 activation and has a role in the development and progression of breast cancer." (PMID 41348684, 2025). "Additionally, CCND1, overexpressed in more than 50% of mammary tumors, was downregulated significantly by both treatments, though the FEO-CSNPs were more potent (p = 0.005105)." (PMID 40284420, 2025). "Long non-coding RNA (lncRNA) DILA1 could interact with the Thr286 of Cyclin D1 for repressing its phosphorylation and subsequent degradation, thereby promoting the Cyclin D1 protein expression and finally contributing to tamoxifen resistance in breast cancer." (PMID 40224178, 2025). "Based on the codominant and recessive models, carriers of the AA genotype are nearly 3.5 times more susceptible to BC than other individuals, and the AA genotype of CCND1 A870G may be a significant factor for breast cancer." (PMID 40321701, 2025).